ECM1 (extracellular matrix protein 1)
Diseases named in the same sentence as ECM1 in open-access papers (continued):
Sharing a sentence is not in itself a finding about the gene and the disease.
asthma (5 papers, 2022 to 2025). "Using this framework, one study nominated IL1R1(Interleukin 1 Receptor Type 1), ECM1(Extracellular Matrix Protein 1), and PDLIM4 (PDZ and LIM Domain Protein 4) as causal asthma targets, with additional signals implicating ECM1 in neuro-immune pathways." (PMID 41459491, 2025). "Specifically, in plasma, we found that an increase of one standard deviation in IL1R1 and ECM1 was associated with an increased risk of asthma, while an increase in ADAM19 was found to be protective." (PMID 37809092, 2023). "Additionally, the colocalization analysis of plasma ECM1 and asthma-shared causal variant sites suggests a higher likelihood of it becoming a potential therapeutic target." (PMID 39806440, 2025). "Bayesian co-localization analysis suggested that ECM1 likely shares the same variant of asthma." (PMID 37809092, 2023). "Through colocalization analysis of the seven initially identified proteins, three proteins were identified as potential drug targets for asthma, including ECM1, IL-6 sRa, and layilin." (PMID 39806440, 2025). "Asthma is an allergic disease, and we found that IL1R1 and Layilin are both associated with allergic diseases, whereas ECM1 is related to atopic dermatitis." (PMID 39806440, 2025). "Combined with previous research, our study found that ECM1 and CD200R1 are risk factors for asthma, indicating that we can systematically obtain more experimental data, including GWAS and basic research, to elucidate this further." (PMID 39806440, 2025). "Bayesian co-localization found that ECM1 in the plasma (coloc.abf-PPH4 = 0.965) and in the brain (coloc.abf-PPH4 = 0.931) shared the same mutation with asthma." (PMID 37809092, 2023). "The viewpoints presented indicate that additional research is necessary to investigate the direction of the relationship between ECM1 and asthma." (PMID 37809092, 2023). "In the brain, per 10-fold increase in ECM1 (OR, 1.05; 95% CI, 1.03–1.08) and PDLIM4 (OR, 1.05; 95% CI, 1.04–1.07) increased the risk of asthma." (PMID 37809092, 2023). "Our integrative analysis revealed that asthma risk is causally affected by the levels of IL1R1, ECM1, and PDLIM4." (PMID 37809092, 2023). "As previous research on ECM1 has reported conflicting directions of effects, the relationship between ECM1 levels and asthma remains uncertain." (PMID 37809092, 2023). "Second, Bayesian co-localization firmly advised that ECM1 in plasma (coloc.abf-PPH4 = 0.965) and ECM1 in the brain (coloc.abf-PPH4 = 0.931) shared the same variant with asthma." (PMID 37809092, 2023). "Another study found that ECM1 inhibits the differentiation of Th17 cells in inflammatory diseases of the central nervous system; however, inhibiting Th17 cell differentiation can reduce the occurrence of asthma." (PMID 39806440, 2025). "In contrast, another study found that ECM1 inhibits the differentiation of Th17 cells in central nervous system inflammatory diseases, but the inhibition of Th17 cell differentiation can reduce the occurrence of asthma." (PMID 37809092, 2023). "Moreover, the identified proteins may serve as attractive drug targets for asthma, especially ECM1 and Layilin (LAYN)." (PMID 39806440, 2025). "Additionally, the identified proteins may serve as attractive drug targets for asthma, particularly ECM1 and Layilin (LAYN)." (PMID 39806440, 2025). "Our study demonstrates a causal relationship between genetically determined IL1R1, ECM1, and PDLIM4 plasma protein levels and asthma and, additionally, a causal relationship between ECM1 protein levels in brain tissue representing neurogenic inflammation and asthma." (PMID 37809092, 2023). "Colocalization analysis indicated that ECM1 (coloc.abf-PPH4 = 0.953), IL-6 sRa (coloc.abf-PPH4 = 0.966), and layilin (coloc.abf-PPH4 = 0.975) shared the same genetic variation as in asthma." (PMID 39806440, 2025).
asthma (continued). "Our study demonstrated a causal relationship between genetic determinants, including IL1R1, IL7R, ECM1, CD200R1, ADAM19, IL-6 sRa, and Layilin (LAYN) protein levels, and asthma." (PMID 39806440, 2025). "A causal relationship exists between genetically determined protein levels of IL1R1, IL7R, ECM1, CD200R1, ADAM19, IL-6 sRa, and Layilin (LAYN) and asthma." (PMID 39806440, 2025). "The study identified three potential drug targets for asthma, including IL1R1, ECM1, and PDLIM4." (PMID 37809092, 2023).
cholangiocarcinoma (5 papers, 2013 to 2024). A carcinoma that arises from the intrahepatic biliary tree (intrahepatic cholangiocarcinoma) or from the junction, or adjacent to the junction, of the right and left hepatic ducts (hilar cholangiocarcinoma). "ECM1 is a glycosylated protein secreted extracellularly that was found to contribute to migration and invasion in cholangiocarcinoma cells." (PMID 33407080, 2021). "Increased ECM1 expression has also been noted in laryngeal carcinomas, hepatocellular carcinomas and cholangiocarcinomas where it was correlated with microvessel density, growth, metastasis and poor prognosis." (PMID 24023917, 2013). "We suggest that ECM1 may influence the EMT, and thus metastatic potential, through regulation of MUC1 expression, in accordance with reported correlations of ECM1 expression with metastasis in laryngeal carcinoma and cholangiocarcinoma." (PMID 25499743, 2014). "Indeed, recent studies in a cholangiocarcinoma cell line show that ECM1 downregulation results in reduced migration and invasiveness in in vitro studies." (PMID 24023917, 2013).
inflammatory bowel disease (5 papers, 2013 to 2025). A spectrum of small and large bowel inflammatory diseases of unknown etiology. "Moreover, ECM1 gene is recently found to have a crucial function in M1 macrophage polarisation in inflammatory bowel disease after lipopolysaccharide (LPS) treatment." (PMID 35715992, 2023).
liver cirrhosis (4 papers, 2016 to 2025). "Results revealed that ECM1 expression, tumor size, number of tumor nodules, tumor capsule, vascular invasion, and liver cirrhosis were the independent prognostic factors for both OS and DFS in HCC patients after curative resection (P < 0.05)." (PMID 27460906, 2016). "We evaluated the association between ECM1 expression and clinicopathological characteristics, including age, gender, tumor size, number of tumor nodules, tumor capsule, HBsAg status, serum AFP level, Edmondson’s grade, vascular invasion, Child-Pugh class, stage of liver cirrhosis, and TNM stage." (PMID 27460906, 2016).
lymph node metastases (4 papers, 2012 to 2020). "We demonstrated that higher ECM1 expression (HR = 1.44, P = 0.001), lymph node metastasis (HR = 1.97, P = 0.026), and advanced age (HR = 2.58, P = 0.018) might be considered as independent poor prognostic indicators of OS." (PMID 32292720, 2020). "The ECM1 positive rate in the lymph node metastases was 68.4% (13/19)." (PMID 22284579, 2012). "According to clinicopathologic characteristics, we identified that CRYAB, ECM1, GPX3, and CGNL1 may predict histological grade, UICC stage and lymph node metastasis." (PMID 32292720, 2020). "And ECM1 expression rate in tumor specimen with lymph node metastasis (25/34, 73.5%) was not statistically higher than that without lymph node metastasis (29/43, 67.4%) (Fisher’s exact test, P = 0.623)." (PMID 24779890, 2014). "ECM1 protein expression was positively correlated with estrogen responsiveness and LMVD, but was not correlated with the status of the lymph node metastasis in this study." (PMID 22284579, 2012).
myocardial infarction (4 papers, 2019 to 2025). Gross necrosis of the myocardium, as a result of interruption of the blood supply to the area, as in coronary thrombosis. "During myocardial infarction, ECM1 produced by macrophages and pericytes/vascular cells, binds to the fibroblast surface receptor LRP1, promoting fibrosis." (PMID 39910700, 2025). "One of them is Ecm1, upregulated in the aging heart, contributes to cardiac fibroblast stimulation and fibrosis in aging and myocardial infarction." (PMID 39026350, 2024). "In contrast, another study on heart fibrosis showed that ECM1 led to cardiac fibrosis in myocardial infarction by acting as an intermediary between inflammation and fibrosis." (PMID 36299684, 2022). "This suggests that ECM1 plays a role in cardiac fibrosis in aging and myocardial infarction." (PMID 30789914, 2019).
triple-negative breast carcinoma (4 papers, 2019 to 2024). An invasive breast carcinoma which is negative for expression of estrogen receptor (ER), progesterone receptor (PR), and human epidermal growth factor receptor 2 (HER2). "Significantly higher levels of ECM1 were identified in patients with triple-negative breast cancer compared to other subtypes." (PMID 39040439, 2024).
allergic disease (3 papers, 2022 to 2025). An immune response that occurs following re-exposure to an innocuous antigen, and that requires the presence of existing antibodies against that antigen. "Third, phenotype scanning suggested that IL1R1 (rs7588201) is associated with allergic rhinitis (AR), eczema, and allergic disease; ECM1 in plasma (rs13294) is associated with atopic dermatitis." (PMID 37809092, 2023). "Of the CD4+ helper T-cell lineage, the ECM1 expression was almost prone to Th2 cells, indicating the possible association between ECM1 and allergic reactions." (PMID 36553077, 2022).
colitis (3 papers, 2022 to 2023). Inflammation of the colon. "Extracellular matrix protein 1 (ECM1) is a susceptibility gene for IBD and is highly expressed in DSS colitis models." (PMID 38129886, 2023). "provided experimental evidence on the function of this gene and identified ECM1 as a macrophage‐derived protein in DSS‐induced mouse colitis." (PMID 35715992, 2023). "Mice transplanted with ECM1 knocked-down macrophages, a phenotype unable to polarize towards M1 macrophage, decreased pathological inflammation of colitis in experimental IBD mice, raising a direct interpretation of ECM1 function to regulate the IBD-dependent macrophage lineage." (PMID 36553077, 2022).
endometriosis (3 papers, 2023 to 2026). The growth of functional endometrial tissue in anatomic sites outside the uterine body. "This study aimed to evaluate compartment-specific immunohistochemical expression patterns of HOXA-10, HOXA-11, CD44, β1 integrin, ECM-1, and focal adhesion kinase (FAK) in women with endometriosis-related implantation failure." (PMID 42010698, 2026). "Furthermore, ECM1 (extracellular matrix protein 1)+ and MMP11 (matrix metallopeptidase 11)+ endometrial-type stroma cells were detected in the endometriosis lesions." (PMID 37353907, 2023).
laryngeal carcinoma (3 papers, 2014 to 2017). Carcinoma that arises from the laryngeal epithelium. "ECM1 overexpression is associated with poor prognoses in breast, gastric and laryngeal cancer." (PMID 27770278, 2017).
liver cancer (3 papers, 2016 to 2024). An epithelial or non-epithelial malignant neoplasm that arises from the liver. "This experiment which mainly studies ECM1 in the role of EMT-induced liver cancer metastasis further clarifies the important effect of the migration in liver cancer invasion." (PMID 27460906, 2016). "We also found that ECM1 could induce liver cancer cell migration by EMT, this may provide a new train of thought for HCC effective diagnosis and treatment." (PMID 27460906, 2016). "Interestingly, ECM1 has also been proposed as a novel tumor suppressor gene, with abnormal hypermethylation of its promoter leading to transcriptional downregulation and contributing to the development of liver cancer." (PMID 38172938, 2024).
migraine (3 papers, 2021 to 2023). "The Extracellular matrix protein 1 (Ecm1) gene has been suggested for involvement in brain disorders associated with vascular development such as migraine, stroke, and cervical arterial dissection." (PMID 38107409, 2023). "The resulting subnetwork included 9 genes: migraine-associated genes APOE, LRP1, CARF, CTIF, RNF213, and ECM1; LAMA2, which is associated with vestibular anomalies in mice; and the neurodevelopment-associated genes MYO5A and KLC2." (PMID 37107589, 2023). "The majority of the identified variants were found in genes previously associated with migraine (LRP1, ECM1, CARF, CTIF, RNF213, APOE, SLC35D2), with two different rare LRP1 variants each identified in two unrelated children with vertigo." (PMID 37107589, 2023). "Exome sequencing revealed that she had three rare variants in migraine genes, LRP1 c.13471G>C (p.(Asp4491His)), ECM1 c.1126T>C (p.(Cys376Arg)), and CARF c.1718C>T (p.(Ser573Phe))." (PMID 37107589, 2023).
Sepsis (3 papers, 2021 to 2024). Sepsis is defined as life-threatening organ dysfunction caused by a dysregulated host response to infection. "Our data implied that SHI could attenuate ALI in CLP-induced sepsis mice, which was possibly related to ECM1-associated polarization alteration." (PMID 35153740, 2021). "The study revealed that Shionone mitigated sepsis-induced lung damage by influencing the ECM1/STAT5/NF-κB pathway." (PMID 38675431, 2024). "It has been observed that Shionone inhibits the expression of ECM1 and attenuates sepsis-induced injury in kidney and inflammatory factor levels in serum." (PMID 35141243, 2021). "This indicated that the protective effect of Shionone on sepsis-induced inflammation was mediated by suppression of ECM1." (PMID 35141243, 2021). "In 2022, Yang shed light on the impact of Shionone on sepsis-induced ALI and its mechanism of action via the extracellular matrix protein 1 (ECM1)/signal transducer and activator of transcription 5 (STAT5)/NF-κB pathway." (PMID 38675431, 2024). "In conclusion, the present research demonstrated that ECM1 attenuated sepsis-induced ALI by screwing M1 phenotype to M2 phenotype polarization in CLP-induced mice and LPS-induced macrophage RAW264.7 cells, which was mediated by the ECM1/STAT5/NF-κB pathway." (PMID 35153740, 2021).
atherosclerosis (2 papers, 2013 to 2022). A disease characterized by the build-up of fatty material and calcium deposition in the arterial wall resulting in partial or complete occlusion of the arterial lumen. "A combination of markers such as VCAM-1 and cadherin-5 and LUM and ECM-1 in synovial fluid of RA patients could potentially reflect progression of RA with a corresponding increase in atherosclerosis." (PMID 24010407, 2013). "Many atherosclerosis-related genes, such as ADAMTS2, ECM1, and USP18, showed changes in their expression." (PMID 35806463, 2022).
autoimmune (2 papers, 2020 to 2022). "The pathogenic relevance of autoimmunity to ECM1 in LS has been reevaluated by mouse passive-transfer experiments using intra-cutaneous injections of either a rabbit anti-ECM1 polyclonal antibody or an affinity-purified IgG from ECM1 ELISA-positive LS patients’ sera." (PMID 36553077, 2022).
autoimmune disease (2 papers, 2019 to 2022). A disorder resulting from loss of function or tissue destruction of an organ or multiple organs, arising from humoral or cellular immune responses of the individual to their own tissue constituents. "• ECM-1 suppresses Th17 responses and can be secreted by Th2 immune cells in autoimmune diseases.• ECM-1 can interact with αv integrins and block TGF-β activation." (PMID 31134198, 2019).
cervical cancer (2 papers, 2019 to 2021). A primary or metastatic malignant neoplasm involving the cervix. "The c-Myc/lncRNA-PVT1/miR-486-3p/ECM1 axis might serve as a new target for more efficient diagnosis and treatment of cervical cancer." (PMID 34337069, 2021). "Another study on cervical cancer suggested that c-Myc could upregulate the lncRNA-PVT1 expression, which subsequently releases the inhibition of ECM1 by sponging miR-486-3p, thus enhancing the proliferation and viability of cervical cancer cells." (PMID 34337069, 2021).
Cirrhosis (2 papers, 2022 to 2025). A chronic disorder of the liver in which liver tissue becomes scarred and is partially replaced by regenerative nodules and fibrotic tissue resulting in loss of liver function. "However, the typical pathological features of cirrhosis were significantly improved after cell therapy, of which the most significant improvement was achieved by the administration of ECM1-HF-MSCs." (PMID 35136027, 2022).
Crohn disease (2 papers, 2009 to 2024). A gastrointestinal disorder characterized by chronic inflammation involving all layers of the intestinal wall, noncaseating granulomas affecting the intestinal wall and regional lymph nodes, and transmural fibrosis. "In patients with IBD, such as those with Crohn’s disease (CD), LPS promotes the expression of extracellular matrix protein 1 (ECM-1) in intestinal macrophages, thereby interacting with components of the innate immune system." (PMID 39867340, 2024).
epilepsy (2 papers, 2021 to 2024). A brain disorder characterized by episodes of abnormally increased neuronal discharge resulting in transient episodes of sensory or motor neurological dysfunction, or psychic dysfunction. "Neurological manifestations of the disease, such as epilepsy and neuropsychiatric disorders, can be related to the inhibition by ECM1 of MMP-9 activity, a 10a protein that is strongly expressed in the brain." (PMID 39697925, 2024).
glioblastoma (2 papers, 2021 to 2022). The most malignant astrocytic tumor (WHO grade IV). "Down-regulating the expression of ECM1 via transfecting siRNA could weaken the proliferation and invasion of glioblastoma cells and promote the inhibitory effect of Bru treatment." (PMID 34970146, 2021). "Our findings indicated that Bru could inhibit the proliferation and invasion of glioblastoma cells by suppressing the expression of ECM1, and Bru might be a novel effective anticancer drug for glioblastoma cells." (PMID 34970146, 2021). "In the present study, we aimed to investigate the anticancer effects and the underlying mechanism of Bru in glioblastoma cells, and we found that Bru could induce the cell apoptosis of glioblastoma cells in vitro and in vivo via down-regulating the expression of ECM1." (PMID 34970146, 2021).
Infertility (2 papers, 2025 to 2026). "Furthermore, the protein ECM1, expressed in the epididymis, has been verified and validated as a biomarker for diagnosing various causes of infertility." (PMID 40458181, 2025). "ECM1 was the only significant predictor of infertility from the regression analysis (p = 0.031)." (PMID 41594507, 2026).
keloid (2 papers, 2007 to 2025). An irregularly shaped, elevated mark on the skin caused by deposits of excessive amounts of collagen during wound healing. "In contrast, the late remodeling phase application of ECM1 might be beneficial to prevent scar or keloid formation in respective risk patients." (PMID 41149731, 2025). "Meanwhile, later in the remodeling phase, a controlled ECM1 induction might prevent scar or keloid formation." (PMID 41149731, 2025). "The expression of many components of ECM including collagens, decorin, versican, fibromodulin, intergrins, extracellular matrix protein 1 (ECM-1), syndecan and ESM-1 has been identified in leiomyomas as well as dermal wounds during healing, scars and keloids." (PMID 17718906, 2007).
Lichen sclerosis (2 papers, 2013 to 2021). "Additionally, the high expression level of ECM1 in skin may cause a strong immunity and even induce Lichen sclerosis; thus, ECM1, as a target, may elicit strong immune response rather than self-tolerance." (PMID 33910591, 2021).
lung adenocarcinoma (2 papers, 2021 to 2025). A carcinoma that arises from the lung and is characterized by the presence of malignant glandular epithelial cells. "Excessive ECM1 expression was found in lung adenocarcinoma patients." (PMID 35153740, 2021).